SELENOW (selenoprotein W)
Description:
Plays a role as a glutathione (GSH)-dependent antioxidant. May be involved in a redox-related process. May play a role in the myopathies of selenium deficiency (By similarity).
Synonyms: SelW; SEPW1
Tractability: No criterion of Open Targets' tractability assessment is met for any kind of drug.
Gene: Protein-coding gene on chromosome 19 (47,778,677 to 47,784,686, forward strand). Ensembl gene ENSG00000178980.
Subcellular location: Cytoplasm
Gene Ontology:
Biological process: erythrocyte differentiation
Cellular component: cytosol; cytoplasm
Genetic constraint (gnomAD): Loss-of-function variants: 20 observed, 16.2 expected, observed/expected ratio (o/e) 1.23, 90% interval 0.87 to 1.75. The upper end of that interval is the gene's LOEUF score, 1.75, which puts it in group 6 of 6, group 1 being the genes least tolerant of losing a copy. Missense variants: 124 observed, 110.33 expected, observed/expected ratio (o/e) 1.12, 90% interval 0.97 to 1.3. Synonymous variants: 43 observed, 45.51 expected, observed/expected ratio (o/e) 0.94, 90% interval 0.74 to 1.22.
Homologues: Orthologues: chimpanzee SELENOW (99% identical), mouse Selenow (87% identical), pig SELENOW (68% identical), rat Selenow (67% identical), zebrafish selenow1 (57% identical). Paralogues in human: SELENOV (39% identical), MIEN1 (30% identical).
Diseases named in the same sentence as SELENOW in open-access papers:
SELENOW is named in the same sentence as 34 diseases in open-access papers, as found by Europe PMC text mining. Sharing a sentence is not in itself a finding about the gene and the disease. The quoted sentences say what the papers report.
breast carcinoma (7 papers, 2013 to 2023). "Further on, it has been discovered that piR-36712 plays a pivotal role in suppressing breast cancer cell proliferation through the retroprocessed pseudogene of selenoprotein W (SEPW1), SEPW1P, by inhibiting the expression of SEPW1." (PMID 33194751, 2020). "Overall, considering both the CCLE and LINCS datasets, eight selenoproteins were overexpressed (DIO2, GPX1, GPX4, SELENOI, SELENON, SELENOS, TXNRD1 and TXNRD3) and five were down-expressed (DIO1, GPX2, GPX3, SELENOP and SELENOW) in TNBC compared to all other “non-TNBC” breast cancer subtypes." (PMID 35158912, 2022).
selenium deficiency (3 papers, 2016 to 2025). A nutritional deficiency disease resulting from inadequate selenium levels in the body, which can lead to impaired function of selenoproteins essential for antioxidant defense and thyroid hormone metabolism. "During times of selenium deficiency, the expression of certain selenoprotein genes such as GPX1, GPX3, and selenoprotein W (SELENOW) are more sensitive and thus downregulated compared with “housekeeping” selenoproteins such as deiodinases (DIOs) and GPX4." (PMID 39270936, 2024). "Interestingly, several genes encoding selenoproteins (GPX1, GPX4, SELENON, SELENOM, SELENOF, SELENOW, SELENOT) were also downregulated, suggesting molecular evidence of selenium deficiency." (PMID 40459789, 2025).
anemia (1 paper, 2019). A reduction in the number of red blood cells, the amount of hemoglobin, and/or the volume of packed red blood cells. "Studies show that pathological conditions of induced anemia in mice is linked to reduced glutathione peroxidase and selenoprotein W concentrations, suggesting that these associations may be more evident in anemia." (PMID 31597392, 2019).
Arthritis (1 paper, 2024). Inflammation of a joint. "As SELENOW is differentially regulated under physiological and pathological conditions, further studies are needed to identify the role of SELENOW in various bone defects, including postmenopausal osteoporosis, arthritis-causing bone deformity, and bone-metastatic cancer-mediated osteoporosis." (PMID 38683225, 2024).
Atrophy (1 paper, 2024). Any weakening or degeneration, especially through lack of use. "Collectively, these results suggest that SELENOW KO aggravates muscle atrophy and increases the rate of protein ubiquitination in DEX-induced muscle atrophy of mice." (PMID 39303039, 2024). "We first analyzed the Gene Expression Omnibus (GEO) database (GSE 159952) and found that SELENOW mRNA and protein expression were up-regulated in gastrocnemius (GAS) muscles of DEX-induced muscle atrophy mice." (PMID 39303039, 2024).
fibrosarcoma (1 paper, 2023). A malignant mesenchymal fibroblastic neoplasm affecting the soft tissue and bone. "The relative mRNA expression levels of selenoprotein W (SELENOW), SEPP1, masculoaponeurotic fibrosarcoma K (MafK), CAT, SOD1, SOD2, and NAD (P)H: quinone oxidoreductase 1 (NQO1) genes in TN + SeNPs-AOS group were higher than TN group (p < 0.05)." (PMID 38001826, 2023).
lung carcinoma (1 paper, 2021). "SELENOW also has an antioxidant function and overexpression of SELENOW enhance the resistance of hamster ovary and lung cancer cells on H2O2 cytotoxicity SELENON is ubiquitously expressed in muscle, brain, lung and fetal tissue." (PMID 34116728, 2021).
memory impairment (1 paper, 2024). "Conversely, SELENOW overexpression in the triple transgenic AD mice ameliorates memory impairment and tau-related pathologies, featuring decreased 4-repeat tau isoform, phosphorylation at Ser396 and Ser404, neurofibrillary tangles and neuroinflammation." (PMID 39020075, 2024).
sarcopenia (1 paper, 2024). Progressive decline in muscle mass due to aging which results in decreased functional capacity of muscles. "SELENOW deficiency aggravates sarcopenia by impairing proteostasis in skeletal muscle." (PMID 39303039, 2024). "Here, GO enrichment analysis of DEGs between WT and KO in TA muscle of sarcopenia mice showed that SELENOW KO notably up-regulated the regulation of Rho protein signal transduction." (PMID 39303039, 2024). "Subsequently, we analyzed the data of PMID 35017317 and found that SELENOW mRNA expression was up-regulated in hindlimb skeletal muscle of aging-induced sarcopenia mice." (PMID 39303039, 2024). "Here, we found that the expression level of SELENOW was up-regulated under muscle atrophy and sarcopenia conditions." (PMID 39303039, 2024). "Because of the possible roles of SELENOW in sarcopenia, we identified the expression of SELENOW in skeletal muscle of atrophy and sarcopenia mice." (PMID 39303039, 2024). "Here, we demonstrated that selenoprotein W (SELENOW) containing selenium in the form of selenocysteine functioned in sarcopenia." (PMID 39303039, 2024). "In conclusion, our study indicates that SELENOW is the age-related selenoprotein gene and is important for skeletal muscle protein homeostasis, which provides valuable insights into the relationship between selenium and sarcopenia." (PMID 39303039, 2024).
steatosis (1 paper, 2021). Increased lipid within the cytoplasm of cells. "Amongst the 13 genes, eight (DIO1, GPX2, SEPHS2, SELENOK, SELENOS, SELENOT, SELENOF, and SELENOW) had higher, and five (DIO3, GPX1, SELENON, SELENOO, and TXNRD3) had lower expression in steatosis." (PMID 34869521, 2021). "Of these genes, 11 coded for selenoproteins of which four genes had lower expression (SELENON, SELENOO, GPX1, and TXNRD3) and seven genes had higher expression (SELENOK, SELENOS, SELENOW, GPX2, GXP3, DIO1, and SEPHS2) in steatosis." (PMID 34869521, 2021).
cancer (10 papers, 2013 to 2025). A tumor composed of atypical neoplastic, often pleomorphic cells that invade other tissues. "Further, SELENOW is expressed in the brain and is implicated in EGF signaling and redox regulation, while TIMM8A is involved in mitochondrial function with its role in cancer currently evolving." (PMID 39123468, 2024).
muscular disorders (1 paper, 2016). "Selenoprotein W (SelW) is the first selenoprotein linked to Se deficiency-related muscular disorders." (PMID 27557522, 2016).
SELENOW also shares sentences with these, for which no sentence is quoted: tumor (3 papers); colorectal cancer (2); lung adenocarcinoma (2); multiple myeloma (2); neuroblastoma (2); pancreatic cancer (2); Parkinson disease (2); bacteremia (1); epilepsy (1); Huntington disease (1); infection (1); influenza (1); metastatic cancer (1); muscular disease (1); muscular dystrophy (1); neurodegenerative disease (1); oligodendroglioma (1); osteoporosis (1); postmenopausal osteoporosis (1); pulmonary arterial hypertension (1); triple-negative breast carcinoma (1); type 2 diabetes (1).